CST1 (cystatin SN)
Diseases named in the same sentence as CST1 in open-access papers (continued):
Sharing a sentence is not in itself a finding about the gene and the disease.
gastric cancer (continued). "To explore the effect of CST1 on the ubiquitination of endogenous GPX4 in gastric cancer cells, we used the CST1 knockdown stable cell line MKN45-shNC/MKN45-sh1-CST1/MKN45-sh2-CST1, immunoprecipitated GPX4, respectively, and then detected the Ub level by WB." (PMID 36369321, 2023). "Meanwhile, high expression of CST1 promoted the epithelial-mesenchymal transition (EMT) of gastric cancer cells." (PMID 36369321, 2023). "It is a key experiment to explore the regulation of GPX4 stabilization by CST1 by mutating the ubiquitination site of GPX4 and promoting gastric cancer migration and invasion." (PMID 36369321, 2023). "In the present study, we identified CST1 as one of the regulators promoting gastric cancer metastasis." (PMID 36369321, 2023). "Compared with the peripheral blood test results of healthy controls, the expression of circulating CST1 in patients with gastric cancer was increased and was closely related to disease progression." (PMID 36369321, 2023). "Through bioinformatic analysis of our previous transcriptome sequencing data and GEO data set, we found that gastric cancer tissues highly expressed CST1 and enriched the deubiquitination pathway." (PMID 36369321, 2023). "In this study, we performed whole transcriptome sequencing and bioinformatic analysis and found that the prognosis of gastric cancer patients with high CST1 expression was poor." (PMID 36369321, 2023). "In recent years, CST1 was found to be involved in the progression of various cancers, for instance, CST1 increases cell migrative and invasive capacities in gastric cancer." (PMID 35498540, 2022). "The CST1 gene is known to play a crucial role in human gastrointestinal tract cancer, including colon cancer and gastric cancer." (PMID 23711283, 2013). "Previous studies showed that Cystatin SN was present primarily in the cytosolic region of gastric cancer cells, but it was detected in the cytomembrane of colorectal cancer cells." (PMID 23711283, 2013). "In addition, the results suggested inhibition of CST1 prevented the development of gastric cancer development via the AKT pathway, and few studies elucidated the association of CST1 regulating the AKT pathway in gastric cancer." (PMID 39721372, 2025). "These included genes such as SCUBE3, MARCKSL1 and PGK1 in lung cancer, SOX4 and GNAS in breast cancer and hepatocellular carcinoma, HEG1 in hepatocellular carcinoma, PLS3 in pancreatic adenocarcinoma, FBN1 and SPARC in gastric cancer and CST1 in gastric cancer and breast cancer." (PMID 40430098, 2025). "Numerous studies have reported upregulation of CST1 could contribute to gastric cancer by accelerating cancer cell metastasis." (PMID 39721372, 2025). "Currently, the detailed mechanism of CST1 in gastric cancer is unclear." (PMID 39721372, 2025). "CST1 can promote the gastric cancer process by targeting the AKT pathway." (PMID 39721372, 2025). "Besides, CST1 was found to promote gastric cancer by mediating Wnt/β-catenin/TCF signaling as a downstream effector of transcription factor TCF34." (PMID 38424293, 2024). "CST1 promotes gastric cancer metastasis by regulating GPX4 protein stability via OTUB1." (PMID 39605891, 2024). "We hypothesized that CST1 could regulate gastric cancer progression by regulating GPX4 and ferroptosis." (PMID 36369321, 2023). "Our data further confirmed that the overexpression of CST1 may significantly promote the migration and invasion of gastric cancer cells in vitro and enhance liver, lung, and peritoneal metastasis of gastric cancer in nude mice." (PMID 36369321, 2023). "However, the molecular mechanism of CST1 promoting the malignant progression of gastric cancer needs to be further explored." (PMID 36369321, 2023). "Additionally, CST1 expression was demonstrated to be responsible for the elevation of migration and invasion ability of gastric cancer cells by regulating the Wnt pathway." (PMID 36848349, 2023).
gastric cancer (continued). "Furthermore, ROC curve analysis indicated that CST1 improved the sensitivity and specificity of the diagnosis of gastric cancer patients." (PMID 36369321, 2023). "In summary, in the process of gastric cancer metastasis, the expression of CST1 increases." (PMID 36369321, 2023). "Moreover, some data suggested that CST1 is involved in cathepsin inhibition in gastric cancer, promoting its progression by regulating transcription factor HOXC10 and the Wnt signaling pathway." (PMID 36369321, 2023). "CST1 may be used as a new oncological marker and potential therapeutic target for gastric cancer metastasis." (PMID 36369321, 2023). "High expression of CST1 is correlated with advanced pTNM stage in gastric cancer." (PMID 24357805, 2013). "Furthermore, we found that CST1 promotes EMT in gastric cancer." (PMID 36369321, 2023). "Moreover, CST1 improved the sensitivity and specificity of gastric cancer diagnosis." (PMID 36369321, 2023). "We demonstrated that CST1 relieves the ubiquitination of GPX4 through OTUB1, thereby promoting ferroptosis resistance in gastric cancer cells." (PMID 36369321, 2023). "Our analysis showed that compared with normal stomach tissue, CST1, INHBA, ACAN, HSP90AB1, and HSPD1 were the leading five genes that were overexpressed in stomach cancer." (PMID 33828156, 2021). "The stage-based assessment of overexpressed genes showed significant upregulation of CST1, INHBA, ACAN, HSP90AB1, and HSPD1 genes across all stages, including early, locally advanced and metastatic stomach cancer." (PMID 33828156, 2021). "Mechanistically, CST1 enhances cellular antioxidant capacity by stabilizing GPX4 protein while promoting EMT, thereby potentiating peritoneal, pulmonary, and hepatic metastasis of gastric cancer cells." (PMID 40919133, 2025). "CST1 stabilizes GPX4, inhibiting ferroptosis and promoting gastric cancer metastasis." (PMID 39588389, 2024). "Similar to our results, a previous study reported that OTUB1 interacted with CST1 and enhanced the protein stability of GPX4, thereby reducing the ubiquitination of GPX4, inhibiting ferroptosis, and promoting the metastasis and progression of gastric cancer." (PMID 39500879, 2024). "CST1 relieves GPX4 ubiquitination modification by recruiting OTUB1, improving GPX4 protein stability and reducing intracellular reactive oxygen species (ROS), thereby inhibiting ferroptosis and, in turn, promoting gastric cancer metastasis." (PMID 36369321, 2023). "Our research shows that CST1 reduces intracellular ROS by stabilizing GPX4 protein, thereby maintaining the ROS homeostasis of gastric cancer cells in the EMT state, inhibiting ferroptosis and, in turn, promoting the metastasis of gastric cancer." (PMID 36369321, 2023). "Comparison between normal stomach tissue and stomach tumors showed that CST1 (p = 3.97E−21), INHBA (p = 9.22E−20), ACAN (p = 1.08E−19), HSP90AB1 (p = 2.62E−19), and HSPD1 (p = 3.91E−19) were the leading five genes that were overexpressed in stomach cancer." (PMID 33828156, 2021). "Previously, we reported that CST1 was upregulated in gastric cancer tissues, compared with nontumor regions, and clinicopathological analysis showed a significant correlation between high expression of CST1 and pathological tumor, node, metastasis stage." (PMID 24357805, 2013). "Additionally, the expression of CST1 was positively correlated with the clinical stage of gastric cancer, but the difference was not statistically significant." (PMID 36369321, 2023). "Mechanistically, CST1 relieves GPX4 ubiquitination by recruiting the deubiquitinating enzyme OTUB1, improving GPX4 protein stability and reducing intracellular reactive oxygen species ROS, thereby inhibiting ferroptosis and, in turn, promoting EMT and metastasis of gastric cancer cells." (PMID 36369321, 2023).
gastric cancer (continued). "For example, cysteine protease inhibitor SN (CST1) could regulate the protein stability of glutathione peroxidase 4 (GPX4) through OTUB1 and inhibit the ferroptosis of gastric cancer cells, which in turn promoted the metastasis of gastric cancer to the liver, lungs and peritoneum." (PMID 40178680, 2025). "CST1 can promote EMT in thyroid cancer and liver cancer; however, its role in promoting EMT in gastric cancer has not yet been investigated." (PMID 36369321, 2023). "Also, the positive correlation between CST1 and GPX4 expression levels remained unchanged regardless of the degree of gastric cancer tissue differentiation." (PMID 36369321, 2023).
breast carcinoma (21 papers, 2015 to 2025). "The upregulation of CST1 expression is closely associated with poor prognosis in breast cancer patients and colon cancer, consistent with our results verifying the expression of CST1 in esophageal cancer tissues and cell lines by immunohistochemistry (IHC) and western blotting." (PMID 33869274, 2021). "Future studies are needed to uncover the underlying mechanisms of CST1 activity in breast cancer." (PMID 28523467, 2017). "This implies that elevated CST1 in breast cancer could serve as a feasible prognostic factor for patients with breast cancer in risk groups." (PMID 28523467, 2017). "In addition, we also explored the function of the CST1 protein in breast cancer cells through gain or loss of function assays." (PMID 28523467, 2017). "To investigate whether CST1 is linked to clinicopathological variables in breast cancer, we analyzed the correlation between CST1 expression and clinicopathological variables in 244 breast cancer samples." (PMID 28523467, 2017). "For example, TFAP2C regulates TGFBR2 transcription and promotes lung tumorigenesis and EMT, and TFAP2C regulation of CST1 transcriptional activation promotes breast cancer progression and inhibits iron death." (PMID 40995432, 2025). "For example, Liu et al25 reported that CST1 is involved in the development of ER + breast cancer by regulating the ERα/ PI3K/Akt /ERα loop." (PMID 38424293, 2024). "Cystatin-SN’s (CST1) high expression promotes breast cancer and predicts poor prognosis in patients." (PMID 36699376, 2022). "For instance, CST1 expression was elevated in and conferred poor prognosis of breast cancer patients." (PMID 33968941, 2021). "CST1 itself is known to promote proliferation, clone formation, and metastasis in breast cancer cells and high CST1 expression is negatively correlated with breast cancer survival." (PMID 33828156, 2021). "In this study, we found that higher expression of CST1 is positively correlated with longer overall survival for breast cancer (BRCA) and bladder cancer (BLCA), while it is negatively correlated with overall survival for low‐grade glioma (LGG)." (PMID 32920960, 2020). "This is in contradiction with a previous study indicating that elevated CST1 expression promotes breast cancer progression and predicts a poor prognosis." (PMID 32920960, 2020). "Collectively, our study indicates that CST1 cannot only serve as a significant prognostic indicator but also as a potential therapeutic target for breast cancer." (PMID 28523467, 2017). "Next, CST1 overexpression promoted breast cancer cell proliferation, clonogenicity, migration, and invasion abilities." (PMID 28523467, 2017). "We then compared CST1 messenger RNA (mRNA) and protein expression in breast cancer and normal tissue using real-time PCR (RT-PCR), western blotting, and immunohistochemistry (IHC)." (PMID 28523467, 2017). "In the current study, we found that CST1 was generally upregulated in breast cancer at both mRNA and protein level." (PMID 28523467, 2017). "Collectively, these data indicated that overexpression of CST1 was coincident with tumor progression, which suggests CST1 as a tumor promoter in breast cancer." (PMID 28523467, 2017). "In the current study, we analyzed microarray data from the TCGA database and revealed that CST1 was upregulated in breast cancer compared with normal tissues." (PMID 28523467, 2017). "CST1 expression was significantly upregulated in breast cancer tissues compared with the adjacent normal tissues." (PMID 28523467, 2017). "Consistent with the microarray data, CST1 was upregulated both at mRNA level and protein level in breast cancer tissues compared with corresponding adjacent normal breast tissues." (PMID 28523467, 2017). "As far as we know, our study is the first scientific analysis to assess the expression, clinicopathologic significance, prognostic value, and functional effect of CST1 in breast cancer." (PMID 28523467, 2017).
breast carcinoma (continued). "To investigate the function of CST1 in breast cancer, we exogenously overexpressed CST1 in two breast cancer cell lines, BT-549 and MDA-MB-415." (PMID 28523467, 2017). "To investigate the role of CST1 in tumorigenesis, we screened human colon and breast cancer cell lines and discovered that CST1 was highly expressed in and was secreted into the culture medium by SW480 and MDA-MB-231 cells." (PMID 28383558, 2017). "In accordance with this, the Kaplan–Meier survival analysis demonstrated that the OS and DFS of breast cancer patients with high CST1 expression were worse than those with low CST1 expression." (PMID 28523467, 2017). "To explore the function of endogenous CST1 in breast cancer, we knocked down CST1 expression in BT-474 and MDA-MB-468 cells by transiently transfecting two independent siRNAs against CST1." (PMID 28523467, 2017). "And finally, suppression of metastasis has been found to be correlated with reduced expression of CST1 in breast cancer cell line." (PMID 26569312, 2015). "For example, CST1 is highly expressed in Luminal B breast cancer cells, SEMA3B is highly expressed in HER2-positive breast cancer cells, while SEMA3B stands out in the analysis of progression-free survival, and PLAT is highly expressed in basal-like breast cancer cells." (PMID 39493752, 2024). "In the Luminal A group, CST1 exhibited the largest log2 fold expression increase (3.1); a previous study suggested CST1 may function as a significant prognostic indicator and breast cancer therapeutic target." (PMID 35317849, 2022). "CST1 also promoted the malignant function of breast cancer cells." (PMID 33968941, 2021). "The overexpression of CST1 promotes the migration and invasion of breast cancer cells." (PMID 34194498, 2021). "Recent study reported that elevated expression of CST1 may promotes breast cancer progression and predicts a poor prognosis." (PMID 31692905, 2019). "Furthermore, the primary goal of this study is to assess the predictive impact of CST1 expression on recurrence, metastasis, and survival in patients with surgically resected breast cancer." (PMID 28523467, 2017). "By contrast, knockdown of CST1 attenuated these malignant characteristics in breast cancer cells." (PMID 28523467, 2017). "Collectively, our study is the first to clarify that CST1 could promote cell proliferation and clone formation, migration, and invasion in breast cancer cells." (PMID 28523467, 2017). "Interestingly, the prognostic effect of CST1 is especially strong in stratified survival analysis of breast cancer, according to the factors attributed to worse outcome." (PMID 28523467, 2017). "Collectively, these data indicate that CST1 could promote migration and invasion in breast cancer cells, at least in part, through the enhancement of EMT." (PMID 28523467, 2017). "Taken together, our findings demonstrate that CST1 was highly expressed in breast cancer and suggests that CST1 might be a potential therapeutic target." (PMID 28523467, 2017). "Furthermore, the expression of CST1 was relatively higher in breast cancer cell lines compared with the immortalized human breast epithelial cell line 76N-tert." (PMID 28523467, 2017). "In our present study, CST1 may promote proliferation and metastasis of breast cancer by regulating cell cycle and inducing EMT process." (PMID 28523467, 2017). "Therefore, this study was aimed to investigate the expression and the role of CST1 in breast cancer." (PMID 28523467, 2017). "As shown in the clinical data, CST1 expression correlated with metastasis of breast cancer." (PMID 28523467, 2017). "CST1 was upregulated almost fourfold in breast cancer tissues compared with normal breast tissues." (PMID 28523467, 2017).
breast carcinoma (continued). "Finally, the current results indicate that upregulation of CST1 is a risk factor for tumor recurrence and metastasis, and its expression associated with clinicopathological parameters may act as an independent predictor for patient survival and a therapeutic target in breast cancer patients." (PMID 28523467, 2017). "Therefore, high CST1 expression could identify a subgroup of breast cancer patients with worse prognosis." (PMID 28523467, 2017). "Strikingly, high CST1 expression could also predict poor overall survival of breast cancer patients and different subgroups with ER status, PR status, HER-2 status (negative), tumor size, tumor status, lymph node metastasis status (positive), TNM stage (III), or histological stage." (PMID 28523467, 2017). "Thus, CST1 may serve as a novel prognostic biomarker and a potential therapeutic target for breast cancer treatment." (PMID 28523467, 2017). "Thus, we investigated the effect of CST1 on migration and invasion in breast cancer." (PMID 28523467, 2017). "All of these results suggest that the CST1 could exhibit oncogenic functions in breast cancer." (PMID 28523467, 2017). "Up-regulated expression of COL10A1, MMP11, CST1, GJB2, MMP1, MMP13, and CEACAM6; down-regulated expression of ADH1B, CIDEC, THRSP, GPD1, TIMP4, FABP4, and SCARA5 genes was common in breast cancers of the two populations." (PMID 31292488, 2019). "However, the prognostic significance and function of CST1 in breast cancer remains unknown." (PMID 28523467, 2017). "In the present study, CST1 was dramatically increased in breast cancer cell lines, and most of breast cancer tissue samples compared with adjacent non-cancer controls at both mRNA and protein levels." (PMID 28523467, 2017). "Besides, overexpression of CST1 significantly enhanced the number of colonies of BT-549 and MDA-MB-415 cells, suggesting that CST1 induced the colony-forming ability in breast cancer." (PMID 28523467, 2017). "Nonetheless, the effect and mechanisms of CST1 in breast cancer has not yet been elucidated." (PMID 28523467, 2017). "In addition, IHC staining of breast cancer samples revealed that CST1 is predominantly located in the cytoplasm and highly expressed in breast cancer tissues compared with adjacent non-malignant controls." (PMID 28523467, 2017).